EGF (epidermal growth factor)
Diseases named in the same sentence as EGF in open-access papers (continued):
Sharing a sentence is not in itself a finding about the gene and the disease.
breast carcinoma (continued). "For example, we observed EGF-induced COX-2 expression in HNSCC cell lines but not in breast cancer, colorectal cancer or lung cancer cell lines." (PMID 25595899, 2015). "For two human estrogen-responsive breast cancer cell lines (namely, MCF-7 and ZR-75-1 cells), it has been shown that (+)-aeroplysinin-1 blocks their EGF-dependent proliferation, claiming that this observed effect was caused by an inhibitory effect of (+)-aeroplysinin-1 on EGFR phosphorylation." (PMID 26703630, 2015). "Moreover, we provided in vitro evidence that Anxa2 is required for EGF-induced EMT, as well as in the migration and invasion of breast cancer cells." (PMID 26307676, 2015). "Moreover, knockdown of Anxa2 impaired EGF-induced EMT, as well as the migration and invasion of breast cancer cells in vitro." (PMID 26307676, 2015). "Mifepristone inhibits growth induced by EGF in vitro and it may block the activation of IGF-1 signaling in some breast cancer cell lines." (PMID 26146614, 2015). "Given the important function of EGFR signaling in EMT induction in breast cancer, we speculate that Anxa2 promotes EMT via the activation of the EGF/EGFR pathway." (PMID 26307676, 2015). "Gab2 is essential for epidermal growth factor (EGF) signaling and breast cancer cell proliferation." (PMID 26095858, 2015). "However, when extracellular signal-regulated kinases 1 and 2 (ERK1/2) were activated by coincubation with epidermal growth factor (EGF), ERβ1 agonist DPN induced proliferation in breast cancer cells." (PMID 25874233, 2015). "E2 signaling interacts with IGF-I and EGF pathways, at different levels, for example, through the rapid activation of IGF-IR and EGFR receptors and with the consequent induction of MAPK activation in breast cancer cells." (PMID 26258011, 2015). "Most importantly, we found that PYK2 depletion markedly reduced EGF/HRG-induced MMP9 transcription and its subsequent gelatinase activity in SKBR3 cells, as determined by zymography assay, implying that PYK2 plays an important role in breast cancer metastasis." (PMID 26084289, 2015). "Both EGF and HRG induced rapid phosphorylation of PYK2 in the three breast cancer cell lines." (PMID 26084289, 2015). "Membrane ruffles and lamellipodia could hardly be detected in either EGF- or HER-induced PYK2-depleted cells, suggesting that PYK2 depletion markedly affects early events of the migratory response in these three breast cancer cell types." (PMID 26084289, 2015). "The WASL-dependent formation of invasive membrane protrusions has been identified as an important mechanism of triggering invasive behaviour of human breast cancer cells, and can be induced by several pathways including estrogen-, PDGF- and EGF-induced signaling." (PMID 26657485, 2015). "To focus on cytokines and growth factors specifically produced by ASCs (EGF, FGF, HGF, SDF, IL6, IL8, IL10) or epithelial breast cancer cells (EGF, FGF, HGF) known to be relevant in tumorigenesis, we carried out Q-PCR analyses both on ASCs or primary breast cancer cells, before and after co-culture." (PMID 24327602, 2014). "We evaluated proliferation of MDA-MB-231, EGF-dependent breast cancer cells lacking estrogen and progesterone receptor expression as well as human EGF-receptor 2 (HER2) amplification (triple-negative)." (PMID 25373734, 2014). "IGF-I and EGF are potent mitogens for breast cancer cells inducing cellular proliferation and promoting the invasiveness and endocrine- or chemotherapeutic resistance of T-47D and MCF7 breast cancer cells." (PMID 24779681, 2014). "Additionally, knockdown of Gi2α slightly reduced EGF-, bFGF-, or IGF-1-induced breast cancer invasion." (PMID 24521094, 2014). "Moreover, overexpression of EGFR and HER2, whose ligand (i.e. the epidermal growth factor) is capable of inducing PKD1 activity, was observed in antiestrogen-resistant breast cancers." (PMID 25287328, 2014).
breast carcinoma (continued). "In breast cancer cells, NTSR1 activation alters many cellular effects having oncogenic characteristics including proliferation, survival, adherence, migration and invasion, with a synergic effect between NTS and EGF on cellular migration and invasiveness." (PMID 25249538, 2014). "In the present study, we found that Giα proteins not only regulated SDF1-mediated invasion of breast cancer (data not shown), but also controlled EGF-, bFGF-, IGF-1- and serum-induced MB231 invasion." (PMID 24521094, 2014). "In the studies of breast cancer cells, PTK6 has been reported to enhance EGF-induced cellular migration, while overexpression of PTK6 was reported to increase cellular invasive potential by inducing epithelial mesenchymal translation (EMT) in prostate cancer cells." (PMID 24788754, 2014). "EGF enhances tumor cell proliferation, migration, invasion, and EMT, and thus it should be taken into account when we consider joint activities of microenvironmental factors on breast cancer metastasis." (PMID 24369447, 2013). "The pro-migratory effect in MDA-MB-231 cells was specific to TGF-β1 since treatment of cells with Epidermal growth factor (EGF), a known inducer of breast cancer cell chemotaxis did not enhance migration." (PMID 23457587, 2013). "To study whether ectopically expressed Vav1 in breast cancer cells is functionally active, we stimulated MCF-7Vector and MCF-7Vav1 cells with EGF and AU565Vector and AU565Vav1 with CSF1 for various time intervals." (PMID 23342133, 2013). "A highly invasive and metastatic human breast cancer cell line, MDA-MB-231, was used because of the extent of characterization of this cell line, including its migration behavior in the presence of EGF or SDF-1α gradients using conventional Boyden chamber." (PMID 23869217, 2013). "In the present study we investigated the migratory activity of the two hybrid cell lines M13MDA435-1 and M13MDA435-3 in dependence of EGF and SDF-1α stimulation in comparison to M13SV1-EGFP-Neo breast epithelial cells exhibiting stem cell characteristics and HS578T-Hyg breast cancer cells." (PMID 22487193, 2012). "Consistently in this study, we noticed that when MDA-MB-231 and MCF-7 breast cancer cells were pretreated with AG1478, EGF-induced EGFR phosphorylation was blocked, and resulted in the inhibition of EGF-stimulated ERK1/2 phosphorylation and cell proliferation (data not shown)." (PMID 22476347, 2012). "Thus in our studies, we aimed to determine the effect of EBP50 expression on EGF-induced cell proliferation and activation of EGFR signaling in the breast cancer cell lines, MDA-MB-231 and MCF-7." (PMID 22476347, 2012). "Moreover, MTF-1 has been shown to be critical for the DNA synthesis induced by epidermal growth factor (EGF), which has a profound role in breast cancer." (PMID 22852056, 2012). "Thus, both the EBP50 gain-of-function and loss-of-function studies by CCK-8 and BrdU incorporation assay demonstrated that EBP50 inhibited EGF-induced cell proliferation in MCF-7 and MDA-MB-231 breast cancer cells." (PMID 22476347, 2012). "Indeed, a similar connection between EGF or bFGF and EMT was previously shown in human breast carcinoma cell line, PMC42-LA, and tubular cell lines." (PMID 22134360, 2012). "Additionally, invasive breast cancer cells, MDA-MB-231, undergo metastasis in vivo based on the communication between their secreted factors, colony stimulating factor-1 (CSF-1) and EGF, which are growth factors released by surrounding macrophages." (PMID 22174624, 2011). "The greatest induction of a purinergic receptor upon EMT induction was seen for P2X5, where EGF induced a 4.6-fold increase; suggesting that elevated P2X5 may be a characterizing feature of the metastatic phenotype of some breast cancer cells." (PMID 21850275, 2011). "EGF by itself can increase H2O2 levels and, thus, may be a critical factor in oxidative stress-induced breast cancer." (PMID 20809984, 2010).
breast carcinoma (continued). "EGF withdrawal was previously documented to transform human breast epithelial cell line HMT-3522, where EGFR suppression was posited to promote estrogen-responsive breast cancer." (PMID 20809984, 2010). "Surprisingly, stimulation of canine mammary tumor cells (CMT25) shows that EGF, but not estrogen or progesterone, upregulates PAD2 transcription and translation suggesting EGF regulation of PAD2 and possibly citrullination in vivo." (PMID 20668670, 2010). "Thus, we examined the effect of hormones and growth factors such as E2, EGF, prolactin and P4 on PAD2 expression in canine mammary epithelial cells using two canine mammary tumor-derived cell lines: CMT12 and CMT25 cells." (PMID 20668670, 2010). "We sought to examine how a combination of EMT inducers (EGF, ST), which each have different cellular effects and speed of action, influence the expression of the E-cadherin repressor gene set and downstream EMT effectors in this breast carcinoma cell line." (PMID 19604397, 2009). "Although somewhat upregulated by individual treatments with EGF or ST, Zeb2/SIP1 was repressed in the combined treatment at all timepoints suggesting this Zeb family member is less likely to be involved in Snail1-driven breast cancer EMT." (PMID 19604397, 2009). "Indeed, such a scenario is supported by experiments in which the expression of the isolated PH domain of Gab1 suppressed EGF-induced ERK and AKT activation in breast cancer cell lines." (PMID 19737390, 2009). "In addition, overexpression of caveolin-1 in the MCF-7 breast cancer cell line has been shown to modulate EGFR activation levels and EGF-induced EGFR signaling." (PMID 19816600, 2009). "In accordance with our hypothesis, EGF-stimulated migration was significantly reduced by PD153035 in both MDA-MB-231 and MCF-7 breast cancer cells (P = 0.0004 and P = 0.0006 at the end points, respectively)." (PMID 18435854, 2008). "It is suggested that some breast cancers retain EGF sensitivity observed with nonmalignant mammary cells, while it is lost in others." (PMID 18179684, 2008). "Thus, we analyzed the effect of EGF on S100A7 expression in MCF-7 and MDA-MB-468 breast cancer cell lines." (PMID 18320059, 2008). "Using oligonucleotide sequences, which are specific for the HER2 promoter, the ability of nuclear extracts from non-treated, primary breast cancer cell cultures to bind to the DNA response element was compared to cells treated with bFGF and EGF." (PMID 17060941, 2006). "To evaluate the effects of oestrogen, of EGF and of previously identified BCAR genes involved in oestrogen-independent growth of the human breast cancer cell line ZR-75-1, we determined the global gene expression in these cells by using UniGEMV2 cDNA microarrays." (PMID 15642172, 2005). "In vitro, IGFBP-3 promotes EGF in HER-2-overexpressing T47D and Hs578T breast cancer cells." (PMID 15642160, 2005). "A study of a breast cancer cell lines stimulated with EGF showed an increase in MMP9 but not MMP2, but this increase was not inhibited by the tyrosine kinase inhibitor PD153035." (PMID 15083203, 2004). "In contrast, LEA.92 was undetectable on oncogenically transformed or established lines of mammary carcinoma cell lines which were independent of EGF or anchorage formation for growth and were highly tumorigenic." (PMID 8123470, 1994). "However, in some breast cancer cells, it was found that the uPA system inhibited migration, independently of its protease activity, acting as a negative modulator of EGF-dependent motility." (PMID 39859388, 2025). "In vitro studies with breast cancer cell lines indicated that transfected HPV E6 and E7 could enhance HER-2 expression and confer an EGF-independent in vitro proliferation, suggesting a possible mechanism for how HPV infection might contribute to breast cancer progression." (PMID 38507429, 2024). "Thus, by promoting EGF signaling, PBX1 could help breast cancer cells survive estrogen receptor blockade." (PMID 39358487, 2024).
breast carcinoma (continued). "Additionally, breast cancer cells do not elongate in response to TGFβ stimulation, suggesting that EGF, but not TGFβ, stimulates the acquisition of an elongated phenotype via DOCK4." (PMID 38762624, 2024). "Cisplatin suppressed both overall and EGF-specific endocytosis in TAMs by bidirectional mode: suppression of positive regulators and stimulation of negative regulators of endocytosis, with strongest effect on synaptotagmin-11 (SYT11), confirmed in patients with breast cancer." (PMID 36960065, 2023). "Moreover, the simultaneous ectopic expression of GEP100 and ARF6 in epithelial-like breast cancer cells resulted in the EGF-dependent conversion from noninvasive to invasive breast cancer cells." (PMID 37834383, 2023). "Indeed, EGFR and c-Src are expressed and could be activated by EGF, suggesting that the EGFR/c-Src signaling is intact in breast cancer cell lines." (PMID 33407765, 2021). "In another study, curcumin also inhibited the basal phosphorylation of Akt/PKB in breast cancer cells but not directly, suggesting that it could be due to the decrease in EGF-induced EGFR activation that was observed." (PMID 34867402, 2021). "Decorin down-regulation is mediated by PDGF, EGF, IGF-I, TGF-β and principally by bFGF secreted by the stromal cells themselves acting in an autocrine manner, as well as that released by the neighboring aggressive breast cancer cells establishing a paracrine effect." (PMID 33924197, 2021). "A recent study demonstrated that rapid phosphorylation of SphK2 by epidermal growth factor (EGF) or phorbol 12-myristate 13-acetate (PMA), a known tumor-promoting agent, resulted in an increase in kinase activity and thus enhanced EGF-induced chemotaxis of human breast cancer cells." (PMID 34071409, 2021). "Hence, FIPI-mediated inhibition of choline production might be another mechanism by which this PLD inhibitor might impair EGF-induced calcium release in MDA-NEO and MDA-HER2 breast cancer cells." (PMID 33832505, 2021). "Further experiments on HCC1143 cells demonstrated that EGF-mediated increases in MAPK activation reduced basal STAT3 activation in a MEK dependent manner, strengthening the connection between MAPK signaling and STAT3 activation in human breast cancer cell lines." (PMID 33062958, 2020). "In this study, we screened out a non-classical PKCδ/MAPK/ERK signaling pathway involved in EGF-induced PN-1 up-regulation in breast cancer cells, first provided the evidence that PN-1 could be up-regulated by EGF/EGFR/PKCδ/MEK/ERK signaling pathway." (PMID 31501409, 2019). "In addition, TAMs can excrete cytokines such as epidermal growth factor (EGF), PDGF, VEGF, CCL2, CXCL8 to promote angiogenesis; participate in CSF1 (secreted from breast cancer cell) and EGF (contributed by activated macrophages) feedback loop to cause metastasis; and accumulate in hypoxic area." (PMID 31395836, 2019). "In accord with these results, breast cancer gene array profiling indicated that elevated expression of KLF4 in both MCF10A and MCF7 breast cancer cell lines upregulates transcription of several oncogenes and cell cycle activators such as MAPK, EGF/EGFR, IGF1, CYCLIN D2, CDK1, and CYCLIN E1." (PMID 30613353, 2018). "In addition, ER interacts with EGF receptor and activate tyrosine kinase signaling in breast cancer, and EGF, but not IGF or VEGF, promotes H1395 cell proliferation." (PMID 30190703, 2018). "In MCF-7 human breast cancer cells, SREBP-1c mRNA levels and FASN mRNA levels are high, but SREBP-1a and SREBP-2 mRNA levels are low, and, after addition of epidermal growth factor (EGF), FASN and SREBP-1c mRNA levels are increased, while SREBP-1a and SREBP-2 mRNA levels are not." (PMID 29282029, 2017). "Epidermal growth factor (EGF) is a crucial factor in mammary gland development and EGFR-targeted therapy provides some promising effects in patients with triple-negative (estrogen receptor-, progesterone receptor-, and erb-b2 receptor tyrosine kinase 2-negative) breast cancer." (PMID 29212252, 2017).
breast carcinoma (continued). "Thus, LIMT might represent a new class of EGF‐controlled and ERK‐mediated inhibitors of breast cancer metastasis, which function as tumor‐suppressor lncRNAs." (PMID 27485121, 2016). "We have identified 48 genes that can induce VIM protein in the absence of EGF in the breast cancer cell line MDA-MB-468, suggesting they may be capable of initiating EMT." (PMID 27876705, 2016). "In addition, EGF signaling can induce TWIST through a JAK/STAT3 pathway in epithelial cancer cell lines and the EGF–STAT3-positive correlation has been confirmed in primary breast carcinomas." (PMID 25763355, 2015). "However, in MCF7, a breast cancer cell line, and A549, a lung cancer cell line, autocrine signaling in response to EGF increased in medium without these growth factors, and EGF receptors were activated to promote and increase CSC sphere formation." (PMID 26457068, 2015). "Interestingly, genes that failed to be induced by EGF in PBX1 depleted cells are also significantly enriched in several independent genes datasets obtained from patients characterized by aggressive breast cancers." (PMID 26215677, 2015). "In breast-cancer cells, resveratrol has been reported to inhibit migration and invasion of cells through the suppression of the activation of PI3K/Akt signaling pathway, and epidermal growth factor (EGF)-induced migration, presumably through the EGFR/PI3K signaling pathway." (PMID 23457620, 2013). "M13MDA435 hybrid cell lines, which derived from spontaneous fusion events between M13SV1-EGFP-Neo epithelial cells exhibiting stem cell characteristics and the EGF non-responsive MDA-MB-435-Hyg breast cancer cells, responded to EGF stimulation with an increased migratory activity." (PMID 23667660, 2013). "Analysis of the migratory behaviour by using the three-dimensional collagen matrix migration assay showed that M13SV1-EGFP-Neo cells as well as M13MDA435 hybrid cells, but not the breast cancer cell line, responded to EGF stimulation with an increased locomotory activity." (PMID 22487193, 2012). "Thus CXCR4 overexpression did not override the dependency of these breast cancer cells on the EGF/CSF-1 paracrine loop for in vivo invasion." (PMID 22152016, 2011). "Furthermore, we show that kin17 is necessary for EGF-stimulated cell growth, therefore, treatment targeting kin17 could be combined with neutral EGFR antibody therapy to treat breast cancer." (PMID 21980430, 2011). "EPA did not modify EGFR expression in breast cancer cells; while EGF stimulation significantly increase EGFR phosphorylation to about 140%; co-treatment with EPA/EGF significantly inhibit EGFR activation down to about 40% compared to control non stimulated cells." (PMID 21569413, 2011). "However, IKK can be activated by EGF insome cell types (e.g. estrogen receptor negative breast cancer cells)." (PMID 19343194, 2009). "With regard to breast cancer risk or survival, a number of single nucleotide polymorphisms (SNPs) have been studied in the ESR1 gene, yet none have previously been investigated in the EGF gene." (PMID 18271972, 2008). "Furthermore, our recent observations on inhibition of EGF effect and dissociation of EGFR complex formation with the use of SST in breast cancer cells might serve as a possible mechanism to avert tumour growth resistance and toxicities as proposed in the use of cisplatin." (PMID 38203605, 2023). "Furthermore, preliminary in vitro and in vivo studies were also carried out to assess the use of EGF-conjugated GNPs coated with a combination of hyaluronic and oleic acids combined with NIR laser irradiation for improvement of photothermal therapy as a treatment modality for breast cancer." (PMID 33353068, 2020). "Interestingly, EGFR inhibitor AG-1478 also blocked the upregulation of TAZ mRNA level, but EGF treatment couldn't induce TAZ expression, implicating a heterodimer of ERBB mediating the function of HRG1 in activating TAZ expression in breast cancer cells." (PMID 26885614, 2016).